EPHA2 (EPH receptor A2)
Diseases named in the same sentence as EPHA2 in open-access papers (continued):
Sharing a sentence is not in itself a finding about the gene and the disease.
tumor (continued). "By targeting EphA2-expressing tumor cells, these treatments likely disrupt downstream signaling and induce cell death, but they may also coincidentally reduce the infiltration of immunosuppressive myeloid populations and increase the infiltration and activity of T cells based on our findings." (PMID 40867322, 2025). "Thus, we aim to evaluate how EphA2 expression in the tumor affects the immune landscape in NSCLC." (PMID 40867322, 2025). "Also, the canonical intracellular signaling induced by EphA2 after binding to its natural ligand (Ephrin A1) plays a tumor-suppressive role in epithelial cells by inducing a cascade of reactions beyond the EphA2 (this is called the “forward effect” of EphA2/Ephrin A1 interaction)." (PMID 40943407, 2025). "Although we found decreased lymphocyte populations in lungs bearing EphA2-overexpressing tumors, this result may be confounded by the substantially higher tumor burden in these lungs, compared to the controls, which contained less than a percentage of KPL tumor cells." (PMID 40867322, 2025). "Thus, the combination of EphA2-CAR-T cell therapy with ICIs may represent a valid strategy to overcome the inhibitory tumor microenvironment and enhance CAR-T cell function." (PMID 39596256, 2024). "Notably, TRIM31 (logFC = 1.14), ANXA1 (logFC = 1.05), GBP1 (logFC = 1.01), BIRC3 (logFC = 0.99), APOL1 (logFC = 0.97), IL18 (logFC = 0.94), ANXA2 (logFC = 0.89), BHLHE40 (logFC = 0.83), and EPHA2 (logFC = 0.75) exhibited significant upregulation in tumour tissues." (PMID 38254861, 2024). "Thus, FX12 might be useful in counteracting tumor growth in those cancers where EphA2 has a tumor-suppressive action." (PMID 39596256, 2024). "Therefore, measuring EphA2 released into the bloodstream from the surface of cancer cells might allow for the direct observation of changes in the expression of EphA2 in tumor cells over time." (PMID 39766211, 2024). "Notably, EPHA2 upregulation is associated with an increased risk for malignancy and a poor clinical prognosis in various cancer types, and EPHB4 expression is widely observed in neoplastic cells, correlating with tumor progression." (PMID 38612645, 2024). "EphA2 seems to induce phosphorylation of yes-associated protein (YAP), a transcriptional coactivator that promotes cell proliferation and tissue homeostasis, which may be the mechanism related to tumor drug resistance." (PMID 39839790, 2024). "Furthermore, proteolysis of the ligand-binding domain of EphA2 by metalloproteinases may abolish ligand-dependent inhibition and then induce the tumor-promoting function." (PMID 37816703, 2023). "However, EphA2 also acts as a tumor suppressor under several dysfunctional conditions." (PMID 37816703, 2023). "Although, the mechanism by which cancer cells escape ligand-dependent tumor-suppressive signaling in vivo remains unclear, we have recently elucidated a novel molecular mechanism that regulates the conflicting cellular functions of EphA2 signaling." (PMID 37712876, 2023). "Trivalent CAR-T cells co-targeting HER2, IL-13Rα2, and EphA2 could overcome interpatient variability, achieve a capture of antigens in nearly 100% of tumor cells, avoid antigen escape, and were shown to increase the survival in an orthotopic xenograft model of GBM." (PMID 37443804, 2023). "However, whilst invasive stimuli such as AA, only induce the non-canonical phosphorylation of EphA2 at the leading/invasive edge of the PCa lesion, we can detect an increased expression of total EphA2 deeper within the tumour lesion: this also correlated with poorer overall survival." (PMID 35869144, 2022). "Thus, ephrin-A5 could have been investigated as a potential tumor-suppressing ligand through the interaction with its tumor promoting receptors such as EPHA2, EPHA3, EPHA4, EPHA5, EPHA7, EPHA8, and EPHB2 in sarcomas." (PMID 35563562, 2022). "Combination therapy of anti-EphA2 and anti-PD-L1 may produce a better tumor suppressor effect." (PMID 36478746, 2022).
tumor (continued). "Since the involvement of EPHA2 in PDGFA signaling, we examined whether EPHA2 had roles in tumor growth and invasion of GBM cells through MTT assay an Matrigel-coated transwell assay in the context of PDGF-AA stimulation, which indicated that EPHA2 knockdown decreased viability and invasiveness." (PMID 35105853, 2022). "Furthermore, they observed that exosomal EPHA2 could be informative in predicting tumor progression and in detecting early responses to neoadjuvant chemotherapy." (PMID 35408909, 2022). "However, EphA2 can act as either a tumour suppressor or driver depending on the mode of activation." (PMID 35869144, 2022). "Finally, xenograft tumor models were established using tumor cells expressing different levels of EPHA2 to mimic the secretion of exosomes by tumor cells in vivo, and the metastasis of cancer cells were monitored using the IVIS Spectrum imaging system and Computed Tomography." (PMID 35673569, 2022). "We believe that a short journey into the role of EphA2 in tissue patterning and homeostasis may turn useful to better illustrate its involvement in tumor progression, apparently tumor-context specific but obeying signaling principles common to tissue patterning and repair." (PMID 33572284, 2021). "Therefore, EphA2-SE activates different signaling pathways in different tumor cells." (PMID 33712565, 2021). "Moreover, our observations may illuminate how alterations in the signalling coding downstream of EphA2 dictates whether cell : cell repulsion operates primarily in a tumour-suppressive or a metastasis-promoting mode." (PMID 34819513, 2021). "In addition, EphA2 knock‐down suppressed CC tumour development in the xenograft mouse model." (PMID 33586348, 2021). "For further evaluating whether the interactions of MYOF with EGFR and EPHA2 are shared across tumor types, we analyzed MYOF co-expression with the members of common cell membrane receptor kinase (RTK) family from the proteomic data of 375 cancer cell lines from 22 lineages in CCLE." (PMID 34178975, 2021). "Interestingly, a recent study demonstrated that EGFRvIII, due to its tumor-specific expression, can be successfully used in a SynNotch-CAR system, where it is responsible for turning on the expression of a dual-antigen–targeting CAR (IL13Rα2 and EphA2) at a tumor site." (PMID 34760690, 2021). "Thus, the S897 phosphorylation of EphA2 may work as a stress rheostat, transducing adaptive responses and thereby influencing tumor progression." (PMID 33572284, 2021). "Interaction of progranulin with EphA2 may act in cancer progression and tumour angiogenesis." (PMID 32233022, 2020). "However, mice administered both EphA2-specifc and non-transduced T cells died within 7–8 weeks from non-tumor causes, which deserves further investigation." (PMID 32811512, 2020). "Tumor formation experiment showed that EphA2-WT dramatically increased in vivo tumorigenicity of NPC cells, whereas EphA2-YA slightly did it as compared to endogenous EphA2 knockdown, indicating that Y772A mutation almost abolished the effects of EphA2-WT on the in vivo tumorigenicity of NPC cells." (PMID 32848131, 2020). "Furthermore, pharmacological inhibition of EphA2 by the small molecule inhibitor ALW-II-41-27 reduced the proliferation of SUN-resistant tumor cells, suppressed tumor growth in vivo, and restored the sensitivity of SUN-resistant tumor cells to SUN in vitro and in vivo." (PMID 32814829, 2020). "Several studies reported that EphA2 is selectively upregulated in diverse arrays of cancer including, but not limited to, breast, pancreas, prostate, lung, and most importantly ovarian cancer affecting cancerous cells growth, invasion, and metastasis and angiogenesis and increasing the tumor burden." (PMID 33003468, 2020).
tumor (continued). "Therefore, our results suggest that instead of ablation of both tumor‐suppressive and oncogenic receptor activities, the reversal of the EphA2 oncogenic signaling switch may better correlate with effective HGSC sensitization to platinum‐based chemotherapy." (PMID 32115889, 2020). "EphA2 overexpression on tumor cells could constitute a new antigen for tumor immunotherapy." (PMID 32811512, 2020). "In BL-0293 and BL-0382 tumor models, shorter survival was not only attributed to tumor regrowth, but was driven by unexplained weight loss, possibly caused by the metastatic progression that was mainly seen in the DTX treated group and partially seen in the EphA2-ILs-DTXp group." (PMID 33092175, 2020). "However, when white blood cells (black arrows) were present in the lumen of VM channel formed by EphA2-positive tumor cells (blue arrow) or EphA2-positive glandular cells (blue arrows), along with erythrocytes (asterisks), the cases were excluded from VM count." (PMID 30833656, 2019). "Besides, EphA2-FAK-siRNA-DOPC reduced 62–82% more tumor metastasis than a single group." (PMID 29861465, 2018). "We hypothesized that a bispecific composed of an anti-effector (e.g., anti-LRP6) antibody and an antibody binding to a guide antigen (e.g., a tumor-associated cell surface molecule such as ALCAM, EphA2 or ICAM-1) will modulate potency and cell type selectivity of the anti-effector antibody." (PMID 29335534, 2018). "Furthermore, the presence of Eph2-TEA-VV in co-culture assays with CAR T-cells could strongly enhance the killing of HER2+EphA2+ A549 tumour cells." (PMID 29157300, 2017). "Therefore, EphA2 is a proper candidate for developing targeted GC therapy that could inhibit metastasis and induce cytotoxicity in tumor cells while sparing normal cells." (PMID 29273006, 2017). "Whether or not heterogeneity of a tumor or different mutations acquired by cancer cells in CRC patients can modulate CEACAM1’s effect on EPHA2 activity has yet to be investigated." (PMID 29262644, 2017). "Phosphorylation of RCP at Ser435 by Lemur tyrosine kinase-3 (LMTK3) and of EphA2 at Ser897 by Akt are both necessary to promote Rab14-dependent (and Rab11-independent) trafficking of EphA2 which generates cell:cell repulsion events that drive tumour cells apart." (PMID 28294115, 2017). "Also, other studies demonstrated that repulsive EphA2-RhoA signaling among cancer cells may serve to allow tumor cells to disperse from the main tumor mass." (PMID 27246245, 2016). "EPHA2 kinase activity and pro-tumor effects were found to be correlated with Ser897 phosphorylation mediated by Akt; interestingly, this was a ligand-independent event, whereas binding of ephrin-A1 ligand was sufficient to abrogate EPHA2 Ser897 phosphorylation and therefore EPHA2 kinase activity." (PMID 26073592, 2015). "Collectively, these findings suggest that EphA2 may be an ideal tumor target for cancer therapy." (PMID 22370972, 2013). "Also in non-tumour cells, EphA2 was degraded by Cbl binding to ephrinA1." (PMID 23738943, 2013). "Therefore, our results suggested that up-regulation of membrane-bound ephrin-A1 induced by hypoxia may promote tumor angiogenesis through interaction with its receptor EphA2 on endothelial cells in tumor microenvironment." (PMID 24040255, 2013). "In addition, over expression of receptor EphA2 significantly enhanced tumor growth." (PMID 22824143, 2012). "Silencing the expression of EphA2 receptor also increases the expression of cdx-2 which indicates that knockdown of EphA2 either by ephrin-A1 activation or by silencing interference RNA could be potential in inhibiting the oncogenic effect of receptor EphA2 and tumor growth." (PMID 22824143, 2012). "Thus, EphA2 has been proposed to be involved in tumor-induced angiogenesis." (PMID 21957483, 2011).
tumor (continued). "Furthermore, this patient is positive for human leukocyte antigen (HLA)-A2, allowing us to characterize CD8+ T cell immune response against well-characterized HLA-A2-restricted GAA-epitopes, such as EphA2 883–891 and IL-13Rα 2 345–353, both of which were expressed in this patient's tumor." (PMID 18093336, 2007). "We also obtained histological evidence that EphA2 inhibition suppressed RCC progression, as indicated by the enhanced tumor cell apoptosis revealed using the TUNEL assay." (PMID 41440001, 2025). "Tumor wet weight (1569.9 ± 595.5 vs. 636.5 ± 288.9 mg, p = 0.009) and activation of RhoA and FAK were decreased in the EphA2-knockdown group (p < 0.05 for all)." (PMID 41440001, 2025). "PET/CT images and ex vivo biodistribution data showed a significant reduction in tumor radioactivity uptake, indicating that [68Ga]AJ201 uptake in Panc1 tumors is EphA2-specific." (PMID 40225586, 2025). "Although B7-H3×CD3 and EPHA2/EPHA3 BsAbs and TsAbs are effective preclinically, clinical feasibility and off-tumor toxicity require rigorous validation." (PMID 41209565, 2025). "Our results demonstrate that gallium-68-labeled radiotracers bind to EphA2 with high affinity in vitro across all tested PDAC cell lines and enable expression-dependent tumor detection in vivo within 60 min of radiotracer injection." (PMID 40225586, 2025). "In summary, our findings illuminated the dual roles of EPHA2 in TNBC, influencing both tumor progression and cell death pathways." (PMID 40919148, 2025). "In 2022, it was demonstrated that exosomal EphA2 from TNBC cells was able to increase endothelial cell migration and vascular permeability, thus favoring tumor metastatization." (PMID 40691627, 2025). "Complementing this, m6A “reader” IGF2BP proteins stabilize pro-angiogenic transcripts such as VEGFA and EPHA2, and exosomal transfer of IGF2BP2 from tumor cells can activate endothelial PI3K–AKT signaling to drive vessel formation and metastatic spread." (PMID 41280938, 2025). "EphA2 is overexpressed in more than 90% of NSCLC tissues, where it correlates with poor survival rates and drives tumor growth, metastasis, and survival through mechanisms such as S897 phosphorylation and ERK1/2 activation." (PMID 40181964, 2025). "Overall, our findings illuminated the dual roles of EPHA2 in TNBC, influencing both tumor progression and cell death pathways." (PMID 40919148, 2025). "We confirmed that EphA2 CAR NK cells have a high killing capacity for H460 cells and effectively suppress tumor growth." (PMID 40181964, 2025). "PET imaging and biodistribution studies indicate that [68Ga]AJ201 exhibits a tumor accumulation profile comparable to [68Ga]BCY18469, with slight differences attributed to variations in EphA2 expression across models." (PMID 40225586, 2025). "EphA2, which is endogenously expressed by OVCAR-8 tumor, emerged as a top resistance hit in the α-EphA2-CAR-M screen, confirming the validity of our method, as target loss prevents CAR-M recognition." (PMID 40595560, 2025). "Methods and Results: Analysis of genomic data from the Cancer Cell Line Encyclopedia (CCLE) and The Cancer Genome Atlas (TCGA) revealed elevated EphA2 expression in PDAC, confirmed by immunohistochemical staining of tumor tissue microarrays (TMAs)." (PMID 40225586, 2025). "Novel pan-tumor targeting agents, such as TROP-2, Nectin-4, LAT1, GPC-1, and EphA2, are also under development, and clinical translation of radioligand therapy is anticipated." (PMID 40717183, 2025). "For instance, anti-EphA2 mAbs (EA2 and B233) promoted EphA2 phosphorylation and degradation in cancer cells, and administration of EA2 mAb significantly decreased tumor growth in xenograft model." (PMID 40236294, 2025). "Together, these results confirm that the oncogenic PLEKHA1-TACC2 fusion protein activates the EphA2/AKT/MMP2 signaling pathway through stabilizing EphA2 expression and plays a vital role in tumor VM formation." (PMID 40615663, 2025).
tumor (continued). "Our study further elucidates a functional mechanism where EFNA1 cis-interacts with its receptor EphA2, leading to EphA2 degradation and subsequent activation of the Src/AKT/STAT3 pathway, thereby promoting tumor progression in CC." (PMID 39964764, 2025). "This impairs the tumor cells’ ability to remodel the ECM, highlighting the role of curcumin in targeting the EphA2/PI3K/MMPs signaling pathway to inhibit VM formation in ChM." (PMID 41019994, 2025). "In general, current studies on NPs and TCM formulas targeting VM formation in ESCC primarily achieve their effects by specifically targeting EphA2, blocking the EMT process, improving the hypoxic tumor microenvironment, and mediating ECM remodeling." (PMID 41019994, 2025). "We observed that kinase activity profiles varied between tumor intrinsic subtypes, with a highly hyperactive Phos2 (hyperactivity of PI3K/AKT and mTOR signaling members, PTK2, SRC, EPHA2 kinases) and a less active Phos1 subtype." (PMID 38650175, 2024). "The immunohistochemical staining results of the xenografted tumor tissues revealed that ECM proteins treatment significantly increased the expression levels of VM and EMT‐related markers, including VE‐cadherin, EphA2, and Vimentin." (PMID 39036079, 2024). "It was validated that SNAI1 facilitates tumor progression and metastasis through the PIK3R2/p-EphA2 axis." (PMID 39702326, 2024). "Illustrative of these advancements, a multimodal oncolytic HSV, expressing the shared TAA ephrin A2 (EphA2), elicits a potent acquired antitumor immune response in oncolytic HSV‐resistant murine brain and peripheral tumor models." (PMID 39399642, 2024). "Of note, we previously reported EPHA2 and EGFR to be elevated in the tumor cell compartment of PDAC tissues." (PMID 38650175, 2024). "Western blot analysis showed that tumor cell-derived MVs expressed characteristic marker proteins TSG101 and CD63, along with high levels of EphA2." (PMID 38433190, 2024). "The increased expression of EPHA2, along with other pro-angiogenic molecules, such as VEGF, was found across the microvasculature of GBM, indicating its role in tumour neovascularisation." (PMID 38247816, 2024). "The killing effect of EphA2-CAR-T cells was demonstrated both in vitro and in vivo using DU145 tumor xenograft mice models." (PMID 39596256, 2024). "EEFNA1 encodes EPH protein and is involved in regulating developmental events, while EPHA2 can interact with EPHA1 to regulate the movement and proliferation of tumor cells." (PMID 39256364, 2024). "While numerous studies have explored the expression levels of different molecules in tumor tissues, the current study aims to investigate the expression pattern of certain proteins (ILK, EphA2, and VEGFA) in a sample of LNs from CRC." (PMID 39525153, 2024). "EPHA2 and VEGFA activate both PI3K/AKT and the extracellular signal-regulated kinase 1/2 (ERK1/2) signaling pathways to induce tumor progression by increasing tumor cell proliferation and vasculogenic mimicry." (PMID 38503745, 2024). "Analyzes of EphA2 and ephrinA1 protein and mRNA expressions in ESCC samples revealed that both markers are co-located in the same tumor areas and vascular endothelial cells." (PMID 39839790, 2024). "In our study, we found that EphA2 promoted CSC-associated phenotypes, such as proliferation, sphere formation, colony formation, drug resistance, and tumour initiation, in OSCC cells, suggesting that EphA2 is necessary for OSCC cells to maintain stemness." (PMID 38916835, 2024). "Next, we examined HPAF-II tumor lysates from mice treated with ETC-159 and observed an increase in the phosphorylation of EGFR at Y1068 and EPHA2 at Y588." (PMID 38488003, 2024). "For instance, the interaction of EphA2 with Caveolin-1 (CAV1), an integral membrane protein, leads to the formation of new vessels in the tumor microenvironment of EWS cells." (PMID 39596256, 2024).